CDC42 (cell division cycle 42)
Diseases named in the same sentence as CDC42 in open-access papers (continued):
Sharing a sentence is not in itself a finding about the gene and the disease.
cancer (continued). "Cdc42 (also known as cenG1A or DG43102) is a well-known gene associated with cancer cell proliferation belonging to the Rho family of small GTPases that regulate mitosis, establishment of cell polarity, cell migration, and MAPK signaling." (PMID 31072326, 2019). "The members of Rho GTPases, Rac1, Cdc42, and RhoA, have been considered as classical cytoskeleton regulators associated with cancer cell migratory phenotype." (PMID 31019460, 2019). "According to the Sanger COSMIC database (Catalogue of Somatic Mutations in Cancer), 41 mutations of Cdc42 have been reported in a variety of tumor tissues." (PMID 29596304, 2018). "The identification of cancer-associated somatic mutations in Rac1 and RhoA, and more recently also in Cdc42, has demonstrated that the Rho GTPases appear to have more active roles in cancer progression than originally thought." (PMID 30544828, 2018). "DOCK10 is responsible for activation of the small GTPase Cdc42 during cell invasion and the association of Cdc42 with cancer and EMT has been widely documented." (PMID 29765546, 2018). "Accordingly, overexpression of Cdc42 is implicated in several human cancers and is correlated with poor disease outcome (5, –, 7)." (PMID 30104412, 2018). "Deregulation of CDC42 can alter the normal function of cells and has been associated with cancer development and tumor metastasis." (PMID 28423712, 2017). "Cytosolic CTNND1 drives E-cadherin-deficient cancer cell migration, invasion and metastasis through activation of Rho-family GTPases Rac1 and Cdc42 and inhibition of RhoA activity." (PMID 29228664, 2017). "COX-2 is overexpressed in many cancers and is associated with angiogenesis through the Rac/Cdc42 and PI3K-Ras signalling pathway." (PMID 28173828, 2017). "The results of Gene Set Enrichment Analysis (GSEA) indicated that cells on chitosan substrates increased the genes related to mTOR, eIF4, Cdc42, and Ras signaling pathways, which are associated to the cancer progression and invasiveness." (PMID 28367998, 2017). "In brief, liver inflammation and cancer caused by HBx-induced activation of CDC42 and PPARγ, and followed by disruption of cytoskeleton and lipid metabolism." (PMID 27708241, 2016). "Using the Cancer Genome Atlas dataset, we determined that high Cdc42 expression is associated with poorer progression free survival, and that Cdc42 expression is highest in the proneural and neural subgroups of GBM." (PMID 27486972, 2016). "In recent years, the Rac1/Cdc42 pathway has been extensively studied and implicated in cancer metastasis and EMT-mediated cell migration and invasion." (PMID 26462147, 2015). "In the same pathway MET, TGF-βR, and two members of the Rho-family GTPase, Rac, and cdc42 all implicated in the loss of adherence features and acquisition of migratory and cancer properties were regulated, as well." (PMID 26339654, 2015). "Dysregulation of CDC42 activity has been associated with several disease states and developmental disorders, including cancer." (PMID 26336992, 2015). "Since the oncogenic capacity of the Dbl gene product was isolated and shown to mediate GEF enzymatic activity for the RhoGTPase Cdc42, numerous GEFs have been implicated in the progression of cancer." (PMID 23382862, 2013). "Since recent studies have implicated aberrant Rac1 and Cdc42 activity in human cancer, these Rho GTPases have been proposed as anticancer targets." (PMID 24040362, 2013). "Unlike related members of the RasGTPase family, reports of activating mutations of RhoGTPases, such as Rac1, RhoA or Cdc42 are relatively rare in cancer." (PMID 23382862, 2013). "The hubs, (Rac1, Cdc42, RhoA, and HRas) identified in the network are widely studied proteins due to their association with human cancers and core cellular processes." (PMID 23028658, 2012). "CDC42 is a small GTPase associated with various human cancers." (PMID 40861820, 2025).
cancer (continued). "Therefore, the observed interaction between MISP, IQGAP1, and Cdc42 sheds light on potential mechanisms underlying cancer progression, highlighting promising avenues for further investigation and therapeutic intervention." (PMID 38785491, 2024). "Moreover, TLR signaling by invading pathogens or during cancer-associated inflammation, activate Rac1 and Cdc42 which leads to Nuclear Factor kB (NFκB) transcriptional activity and secretion of inflammatory cytokines such as interleukin-6 (IL-6)." (PMID 37397366, 2023). "KEGG enrichment analysis showed that CDC42 was associated with signaling pathways such as cytokine–cytokine receptor interaction, neutrophil extracellular trap formation, and transcriptional misregulation in cancer." (PMID 37476838, 2023). "Moreover, β1 integrin is also the main target of cell division control protein 42 homolog (CDC42), a member of the Rho GTPase family associated with actin-dependent cytoplasm extension regulation, which was shown to mediate cancer cell - EC interactions." (PMID 36119528, 2022). "CDC42 has been linked to multiple human cancers and is involved in the initiation of many cellular responses during oncogenic processes, such as transition from epithelial to mesenchymal, cell-cycle progression, migration/invasion, tumor growth, angiogenesis, and oncogenic transformation." (PMID 35903355, 2022). "CDC42 small Rho GTPase has also been implicated in cancer cell proliferation and viability." (PMID 35033060, 2022). "Likewise, overexpression of Cdc42 is observed in several cancers, where it is linked to poor prognosis." (PMID 34100887, 2021). "It is noteworthy that Cdc42 also associated with YAP nuclear translocation in cancer cells." (PMID 34650666, 2021). "Some studies showed that CDC42EP3 plays a role in the function of cancer-associated fibroblasts and DNA damage repair, both of which could be adjusted Cdc42." (PMID 33726765, 2021). "Contrary to recent studies that report the identification of new driver mutations in some RHO GTPases members, such as RAC1, RHOA, and CDC42, analysis of cancer genomes has demonstrated that mutations affecting RHO signaling pathways are found at low frequency in a limited spectrum of tumor types." (PMID 34771549, 2021). "Overexpression of Cdc42 is observed in several cancers, where it is linked to poor prognosis." (PMID 34100887, 2021). "In cancer, Rac1 and Cdc42 are mutated, overexpressed and (or) hyperactivated." (PMID 32322580, 2020). "Furthermore, the IPA results indicated that GINS4 is implicated in cancer cell proliferation, cell cycle, apoptosis and metastasis through Rac1 and CDC42 and their downstream signaling pathways: MAPK/ERK pathway, PI3K/AKT pathway and PTEN pathway." (PMID 31754397, 2019). "Our results correlate closely with recent findings where ML141 was shown to inhibit Cdc42 activity not only in human BMSCs, but also in endothelial cells and cancer stem cells by downregulating several pathways implicated in aging and the polarity of stem cell processes." (PMID 29921325, 2018). "In early stage recurrence, the significant pathway associated genes upregulated were MMPs and genes associated with cancer cell adhesion/motility including CDC42, RAC1 while a significant upregulation of WP genes including Wnt4 and Wnt16 was noted during stage IIIc recurrence." (PMID 27902969, 2017). "Further, vertebrate Cdc42 has been implicated in stimulating invadopodia in cancer cell lines, but its function in regulating invadopodia in vivo is unknown." (PMID 26765257, 2016). "In addition, deregulation of CDC42 alters the normal functioning of the cells, accounts for the initiation of signaling pathways and correlates with several pathogenic processes of cancer." (PMID 27769041, 2016). "Furthermore, Cdc42 was implicated in activation of p38 and growth arrest in cancers and was downregulated in proliferating PCa PDX cells in the current study." (PMID 26090669, 2015).
cancer (continued). "Furthermore, Cdc42 over-activity has been associated to cancer, immune diseases and neuronal disorders." (PMID 25360776, 2014). "Cdc42 is overexpressed in a number of human cancers and may be involved in the promotion of tumorigenesis and Cdc42 activity has been implicated in the invasive phenotype which characterizes tumor metastasis." (PMID 24279335, 2013). "Furthermore, Cdc42 has also been implicated in both the transformation and malignant progression of cancer." (PMID 16280046, 2005). "However, once the cancer has developed, the downregulation of CDC42 might be associated with other factors, such as the loss of cell polarity and the acquisition of invasive properties, leading to a worse prognosis." (PMID 37365287, 2023). "Moreover, septins, Cdc42 and Borg proteins play a crucial role in cancer-associated fibroblasts (CAFs), which are non-cancerous cells present in solid tumors that remodel the tumor matrix and promote cancer invasion and angiogenesis." (PMID 29100341, 2017). "We were unable to detect active Cdc42 in our cancer cell lysates, suggesting the need to greatly scale up and further optimize in order to achieve the required signal for this assay." (PMID 41532547, 2026). "CDC42 has been documented to accelerate cancer development through the activation of the integrin β1/FAK/paxillin signal transduction pathway." (PMID 40861820, 2025). "Enhanced CDC42 activity supports genomic stability and activates DNA damage repair pathways in hematopoietic stem cells, mesenchymal stem cells and cancer cells." (PMID 40442778, 2025). "CDC42 can also activate the interactions between cancer cells, endothelial cells, and the extracellular matrix." (PMID 40057606, 2025). "Pak3 is a well-known downstream effector of Cdc42 and Rac1 GTPases that mediates motility and MAPK activation associated with cancer invasion and metastasis." (PMID 40348815, 2025). "JWH-133 also suppresses key pathways linked to cancer progression, such as cyclooxygenase-2 (COX-2) and prostaglandin E2 (PGE2) production, while inhibiting Cdc42 and decreasing the nuclear expression of c-Fos and c-Jun." (PMID 40483537, 2025). "We have shown previously that the PCAIs suppress the levels of RAC1, RHOA, and CDC42 in cancer cell lines." (PMID 40736275, 2025). "Key GTPase subfamilies, Rho, Rac, and CDC42, exhibit increased expression in various types of cancer, especially in late-stage solid tumors." (PMID 41369326, 2025). "LRP8 promotes cancer cell motility by activating CDC42, a protein that stimulates filopodia formation, enabling cells to “crawl” through the cerebral vasculatures." (PMID 40506610, 2025). "Emerging evidence suggests that PP1/PPP1R8 functions as a molecular regulator of directed cell migration by upregulating Cdc42 signaling, potentially enhancing the migratory properties of cancer cells." (PMID 40842996, 2025). "In TNBC, however, the high expression of CDC42 in the primary tumor was clearly correlated with cancer-related death." (PMID 38612766, 2024). "In her work, Murphy concluded that CDC42 and its regulatory and effector protein partners continue to demonstrate an ever-central role in the molecular subversion of signaling in cancer." (PMID 39000458, 2024). "The small Rho GTPase, cell division control protein 42 homolog (Cdc42), has recently been proposed as a promising agent for targeted cancer therapy." (PMID 39458630, 2024). "The GTPase cell division cycle 42 (Cdc42) play important roles in the regulation of cancer cell dormancy." (PMID 38362620, 2024). "NET-DNA can bind to coiled-coil domain containing protein 25 (CCDC25) on cancer cells, activating the integrin-linked kinase (ILK)-β-parvin-ras-related C3 botulinum toxin substrate 1 (RAC1)-cell division control protein 42 (CDC42) cascade within cancer cells." (PMID 39143953, 2024).
cancer (continued). "Here, we describe a novel multiprotein complex (DockTOR) essential for the survival of cancer cells under stress, triggered by the GTPase Cdc42 and a signaling partner Dock7, which includes AKT, mTOR, and the mTOR regulators TSC1, TSC2, and Rheb." (PMID 36711811, 2024). "CDC42, a member of the Rho GTPase group, is crucial in cancer development as it regulates cell movement, microtubule dynamics, EMT, and cell cycle progression." (PMID 39055650, 2024). "Recent studies show that in most human cancers CDC42 is abnormally expressed and promotes neoplastic growth and metastasis." (PMID 39000458, 2024). "These bacterial effects on cell signalling and in particular on Cdc42 are also critical for later steps in cancer progression including cancer invasion (step 7)." (PMID 38535967, 2024). "VCAM1, expressed by cancer cells, restricts iNKT cell motility and inhibits their antigen scanning and activation by DCs via reducing CDC42 expression." (PMID 38332012, 2024). "For instance, 14-3-3 binds directly to RhoGDI1 phosphorylated at Ser174, releasing RhoA, Rac1, and Cdc42, promoting Rho GTPases activation and resulting in increased cancer cell invasion and metastasis." (PMID 39768163, 2024). "This ambiguity makes understanding the role of CDC42-driven polarization in the context of cancer biology challenging." (PMID 38386112, 2024). "The motile behavior of cancer cells is intricately governed by Rho GTPases, with Cdc42 emerging as a central player." (PMID 38646539, 2024). "The overexpression of Cdc42 has been found in various cancer types, such as breast cancer, testicular cancer, head and neck squamous cell carcinoma, melanoma, and CRC." (PMID 39458630, 2024). "The acetylation of mammalian cell division cycle 42 (CDC42), a member of the Rho family of GTPases involved in many crucial signaling pathways in cancer cells, is drastically reduced after bacterial infection." (PMID 36812247, 2023). "Our results demonstrate the dual role of Rac/Cdc42 inhibitors in inhibiting cancer cell and macrophage migration as well as inflammatory cytokines driving metastasis." (PMID 37397366, 2023). "Following the administration with mangiferin, this cancer cell decreased Rac1/Cdc42, WAVE2, phospho-Rac1/Cdc42, Arp2, and Arp3." (PMID 38137424, 2023). "LINC00339 has a known role in promoting the proliferation of several cancers, while there is also evidence to link CDC42 expression with CC invasion and migration." (PMID 36929174, 2023). "Cdc42 belongs to the Rho GTPase family and plays an important role in malignant tumors by regulating the cytoskeleton and microtubule dynamics, cell polarity, and cell cycle progression." (PMID 37476197, 2023). "In our study, we supposed and verified that the CDC42 upregulation can be considered as a signal for afatinib treatment in HPV-related cancers." (PMID 36936942, 2023). "Rac/Cdc42 inhibition induces an antitumor environment via inhibition of both metastatic cancer cells and immunosuppressive myeloid cells in the TME." (PMID 37397366, 2023). "The Rho family, including the GTPases Rho, Rac, and CDC42, are key players in cell growth, invasion-migration, polarity, adhesion, and cancer metastasis." (PMID 38027033, 2023). "Cell division cycle 42 (CDC42) has been shown to regulate cell cycle, migration, invasion and adhesion and has been associated with cancer progression." (PMID 37159502, 2023). "The Rho GTPases Rac and Cdc42 are ideal molecular targets that regulate both cancer cell and immune cell migration, as well as their crosstalk signaling at the TME." (PMID 37397366, 2023). "PAK1 (p21-activated kinase 1) has been shown to be upregulated in many cancers and is activated through phosphorylation by Cdc42 and activates LIMK1." (PMID 37464436, 2023). "Cell division cycle 42 protein (CDC42) is highly expressed in 60% of CRCs and plays an important role in cancer development." (PMID 36812247, 2023).
cancer (continued). "Although the signaling pathway is not clear, CCDC85A promoted EMT, which activates Rac1/CDC42 in various cancer cells." (PMID 37534255, 2023). "Cell division control protein 42 homolog (Cdc42), a member of Rho GTPase family, participates in human cancer cell survival, proliferation, transformation, invasion, and metastasis." (PMID 37191432, 2023). "Cdc42 is a stimulator of filopodia formation and responsible for cancer cells migration and invasion to the ECM." (PMID 37464436, 2023). "In vitro experiments where Fascin-1 was either silenced by siRNA or shRNA or inhibited by a pharmacological inhibitor (compound G2) showed decreased cancer cell migration and impaired Cdc42 and Rac1 activity." (PMID 37511011, 2023). "In conclusion, we have identified CDC42 as a pivotal gene in the pathophysiology of HPV-related cancers." (PMID 36936942, 2023). "Rho-GTPases viz, Rac-1 and Cdc42 are the central regulators of cancer cell migration and invasion and thus metastasis in multiple cancer types." (PMID 37024613, 2023). "Based on the findings above, with various methods and from several aspects, we observed a significance of CDC42 in the pathophysiology of HPV-related cancers." (PMID 36936942, 2023). "Many amino acid residues of CDC42 are prone to mutation and are involved in tumorigenesis, so inhibition of CDC42 or components of its signaling pathway is considered an attractive cancer therapeutic target." (PMID 36812247, 2023). "Cdc42, a key protein that cancer cells need to metastasize, helps them spread through the bloodstream to other parts of the body." (PMID 38041020, 2023). "There have been many attempts to target Cdc42 and other small GTPases in human disease, particularly cancer." (PMID 37114375, 2023). "TAGLN expression was lower in cancer samples compared to normal tissues, and CDC42 expression was negatively correlated with the prognosis of COAD patients." (PMID 37365287, 2023). "Among various types of cancer especially ESCC, the activity of Rho GTPase, in particular those of the family (including most studied members RhoA, Rac1, and Cdc42), have been strongly associated with tumor progression." (PMID 37752569, 2023). "Unfortunately, in spite of being involved in multiple important processes in cancer progression, CDC42 is hard to be targeted with a specific inhibitor, due to its high homology within the other Rho family GTPases and in the wider Ras superfamily." (PMID 36936942, 2023). "TRPV4 can affect tumor angiogenesis and inflammatory microenvironment, intervene in the cytoskeleton-related proteins including RhoA, CDC42, and Rac1, and promote cancer cells EMT." (PMID 37369706, 2023). "Cdc42, an invasive placental component, shown here as intrinsically involved in the activities of the super-giant polyploid cancer cells, developed post-MS and favored the resistant clonogenic survival of DOX-treated MDA MB 231 cells." (PMID 36834647, 2023). "P120-catenin dissociates from adhesion junctions and localizes in the cytoplasm where it can interact with Cdc42, leading to enhanced metastasis and invasion capabilities of cancer cells." (PMID 35154449, 2022). "In this study, we succeeded in developing a novel method to visualize activated Rac and Cdc42 in human cancer FFPE tissues using the R-IHC technique." (PMID 35110666, 2022). "PI3KCB can be activated by Cdc42 and Rac1, and inactivation of PIK3CB can significantly suppress tumor proliferation, metastasis, and invasion in in PTEN-deficient cancers." (PMID 35154449, 2022). "Knowing that Cdc42 is the main effector of StarD13 in these cells, we then looked at the effect of StarD13 depletion on cell protrusion, a main event during cancer migration regulated by Cdc42." (PMID 34958986, 2022). "This article describes the characterization of a panel of MBQ-167 derivatives with the goal of elucidating different activities in different cancer cell types where distinct Rac/Cdc42 GEFs are active." (PMID 36861094, 2022).